LEP (leptin)
Diseases named in the same sentence as LEP in open-access papers (continued):
Sharing a sentence is not in itself a finding about the gene and the disease.
Obesity (continued). "Here, we provided an overview of the cellular interactome of leptin-deficiency-induced obesity, but various limitations arose throughout the study that did not allow us to decipher the mechanistic role of leptin in some pathways." (PMID 38001815, 2023). "Obesity and overnutrition induce inflammation, leptin-, and insulin resistance in the hypothalamus." (PMID 36829858, 2023). "For example, in in vitro studies, leptin has been found to be an important factor for CRC development in obesity, and it should be noted that serum leptin concentrations can be as much as five times higher among individuals with obesity versus those in normal-weight individuals." (PMID 37048534, 2023). "In addition, increased leptin expression in the hypothalamus can aggravate obesity, and enhanced leptin secretion by adipocytes can further contribute to the induction of IR." (PMID 36631836, 2023). "Leptin has been described as a pro-angiogenic factor for its role in vascular permeability and co-function with other growth factors, however, it is also notably upregulated in cases of obesity and T2D." (PMID 37540699, 2023). "Leptin, a protein produced and secreted by adipocytes, increased as fat accumulation increased and is a hormone that induces appetite suppression to control obesity." (PMID 37432154, 2023). "Furthermore, research indicates that leptin not only plays a role in obesity management but also offers potential therapeutic applications." (PMID 38138996, 2023). "Leptin replacement therapies are therefore often used as a treatment for obesity." (PMID 36121552, 2023). "The increased levels of serum leptin in HFD rats found herein are in line with a recent study using a similar HFD-induced obesity design and importantly, the current observation of higher levels of leptin in bone tissue further emphasizes the impact of adiposity in bone remodeling." (PMID 37630764, 2023). "Additionally, pro-inflammatory cytokines such as leptin and adiponectin, which are produced in response to obesity, can trigger pro-inflammation and stimulate cancer development." (PMID 37345115, 2023). "Interestingly, according to the global scientific literature, the increase in circulating concentrations of leptin in contrast to the decrease in adiponectin levels is a striking aspect of both obesity and MetS." (PMID 37571250, 2023). "However, the proliferative activity of leptin under lymphocytes has also been reported in the literature; it can restore and increase the lymphocyte index despite obesity." (PMID 36768983, 2023). "Thus, leptin-induced increased LepR expression appears to be restrained during obesity, thereby contributing to a reduction in leptin’s actions." (PMID 36769012, 2023). "Moreover, in obesity, leptin levels are generally increased and support pro-inflammatory immune responses against the central nervous system (CNS)." (PMID 38026693, 2023). "Many studies have shown that leptin is overexpressed in individuals with overweight and obesity." (PMID 37512149, 2023). "Moreover, increased serum leptin in obesity suppressed anti-Mullerian hormone gene expression through the JAK2/STAT3 pathway." (PMID 36726106, 2023). "Additionally, ablation of tanycytes in mice blunts the transport of leptin into the brain and results in overeating, insulin resistance and obesity." (PMID 38027481, 2023). "The unavailable detailed data of BMI and obesity made it not possible to perform the in-depth influence of obesity and BMI on the association between leptin level and asthma." (PMID 36914629, 2023). "Leptin is critically compromised in the major common forms of obesity." (PMID 38001815, 2023). "Additionally, Th1 polarization in obesity-related asthma is influenced by macrophage activation and correlated with IL-6 and leptin levels." (PMID 38029078, 2023).
Obesity (continued). "Therefore, the main objective of the present study was to investigate the ability of obesity-related leptin doses to modulate the in vitro different effector and regulatory Fel d1-specific CD4+ T cells from patients with persistent cat allergies." (PMID 37954580, 2023). "In addition, PA‐induced high expression of the adipocyte obesity genes Leptin and FABP4, while BMSC‐Exos also significantly and dose‐dependently reduced Leptin and FABP4 protein levels." (PMID 37073893, 2023). "Moreover, a diet based on n-3 PUFAs has a major impact on influencing leptin in the context of inflammation in obesity." (PMID 38068822, 2023). "To explain how dementia and obesity are connected, we focus on the role of leptin and adiponectin." (PMID 37363537, 2023). "Furthermore, selenium supplementation dramatically improved plasma levels of IGF-1, FGF-21, adiponectin, and leptin levels, protecting against diet-induced obesity in mice." (PMID 37755259, 2023). "Leptin is an adipokine that correlates with body fat mass and increases with obesity." (PMID 37770988, 2023). "Therefore, the aim of this study was to elucidate the influence of rs10487505 on leptin mRNA expression and obesity-related parameters." (PMID 36833305, 2023). "In fact, CRF plays a protective role as a moderator in the relationship between obesity and adipocytokines such as leptin and adiponectin, suggesting that people should be engaged in physical activity to improve CRF levels and consequently improve cardiometabolic health." (PMID 37299591, 2023). "However, it was found later that both too little and too much Leptin can lead to obesity, referred to as ‘leptin resistance’." (PMID 37650871, 2023). "It has been shown that leptin-deficient and leptin-receptor deficient mice were shown to have increased bone formation, suggesting the negative effect of increased leptin in obesity on bone formation." (PMID 36926024, 2023). "Obesity-related leptin resistance mechanisms and inflammatory factors (including tumor necrosis factor-α, interleukin-1β, and C-reactive protein) mediate inflammatory responses suppress hypothalamic-pituitary-gonadal axis function in obese men, leading to decreased body testosterone levels." (PMID 37361537, 2023). "Leptin (p < 0.001) and C-peptide (p = 0.009) concentrations were significantly increased, and insulin sensitivity decreased (p = 0.002) in the group with overweight-obesity compared to the underweight-normal weight group." (PMID 37029207, 2023). "Both leptin resistance and the absence of the receptor that mediates most of the actions of this interleukin (IL-1R1) are associated with obesity." (PMID 36674935, 2023). "Therefore, circulating leptin concentrations are correlated with the total amount of fat mass; however, individuals with obesity exhibit an impaired response to leptin despite their hyperleptinemia, suggesting a state of leptin resistance." (PMID 36595188, 2023). "Leptin in obese patients may generate an alternative phenotype (M2), but obesity is also related to a proinflammatory “metabolically activated” phenotype that is both mechanistically and functionally distinct from the classic (M1) phenotype." (PMID 36674935, 2023). "This supports findings that leptin might be involved in EC development through mechanisms beyond obesity-related pathophysiology, including through angiogenesis." (PMID 37509322, 2023). "Adiponectin and leptin are produced by adipocytes and the mammary gland and might play a key role in infants’ growth and obesity prevention." (PMID 36678304, 2023). "Again, in diet-induced-obesity mouse during H1N1 influenza infection, hyperleptinemia was associated with increased mortality, viral spread, and lung inflammation, which were improved by the administration of anti-leptin antibody." (PMID 37217748, 2023). "Furthermore we investigated the relationship of INSL5 plasma levels with classic obesity related parameters such as BMI, waist circumference, fat mass and with leptin plasma levels." (PMID 37297947, 2023).
Obesity (continued). "Indeed, leptin, a proinflammatory adipokine and satiety hormone secreted proportionally to adipose tissue mass, is consistently increased in obesity-induced OA." (PMID 37298701, 2023). "This may be related to the different method and animal they used for model induction, as they built an obesity rat model of episodic HDF for insulin leptin resistance and lipid perception deficits." (PMID 37893758, 2023). "Hypothalamic Slug–elicited epigenetic reprogramming may act in concert with Sh2b1, SOCS3, PTP1b, and additional regulators to promote leptin resistance and obesity." (PMID 36512408, 2023). "Considering that WKYMVm inhibits food intake in HFD‐induced obesity, we checked whether WKYMVm attenuates leptin resistance." (PMID 37603580, 2023). "The authors postulated that additional factors, including altered adipokine levels such as increased leptin and reduced adiponectin, and hyperinsulinemia might potentially have mediated the effects of obesity on BMD in diabetes." (PMID 36875399, 2023). "Additionally, obesity influences the secretion of various adipokines, such as leptin and adiponectin, which are known to play significant roles in reproductive health." (PMID 38264286, 2023). "Leptin is a master regulator of body weight and energy homeostasis that is dysregulated in obesity." (PMID 37002197, 2023). "Leptin has an anti-obesity effect that decreases adiposity but maintains muscle mass." (PMID 36982473, 2023). "However, leptin resistance contributes to diet‐induced obesity, showing a decreased ability of leptin to suppress food intake or increase body energy use." (PMID 37603580, 2023). "Leptin is closely related to obesity, features of T2DM and the progression of breast cancer." (PMID 37233716, 2023). "Collectively, our results suggested that M1 macrophage polarization was enhanced in the female mice with obesity-related neutrophilic airway inflammation, and leptin/obR signaling may affect M1 macrophages." (PMID 37488474, 2023). "Recent studies have shown evidence linking sirtuins and various metabolic pathways like aging, obesity, and diabetes through the modulation of various hormones like leptin, ghrelin, melatonin, and serotonin, thereby influencing neurodegeneration in ENS and CNS." (PMID 37629273, 2023). "Leptin resistance can either be a pathological state, for example, in diet-induced obesity (DIO) or in a hyperleptinemia state, or it can be an adaptive response and physiological phenomenon to allow shifts in the body weight set point, for example, in seasonal animals." (PMID 38089973, 2023). "This correlation can be explained by the inhibitory effect of vitamin D on leptin secretion by adipose tissue because hypovitaminosis D contributes to leptin resistance, and because obesity-induced hyperleptinemia decreases the conversion of vitamin D to 25-hydroxy vitamin D." (PMID 37834125, 2023). "On the other hand, obesity and excess subcutaneous fat increase leptin levels." (PMID 37299398, 2023). "Furthermore, COBL, MKX and MYOC expression in the subcutaneous AT of children is related to obesity and parameters of AT dysfunction and metabolic disease, such as adipocyte size, leptin levels and HOMA-IR." (PMID 36834493, 2023). "The effect of micronutrients on obesity may occur through changing leptin concentrations in the blood, which control food intake and energy expenditure, leading to changes in adipose tissue mass, and also by regulation of the inflammatory response." (PMID 36992905, 2023). "Increased levels of leptin, as commonly occurs in obesity, may lead to placental leptin resistance and decreased amino acid transport activity, thereby reducing nutrient availability required for fetal growth." (PMID 37111410, 2023). "WAT serves as a crucial source of leptin, a significant adipokine involved in obesity development." (PMID 38138996, 2023).
Obesity (continued). "Whereas the anabolic effect of muscle mass on bone in older adults may be partly explained by mechanical loading, the adverse effect of obesity on bone is possibly mediated by low-grade inflammation, higher leptin and lower adiponectin levels." (PMID 36977715, 2023). "In addition, we successfully established optimal cut-off values for leptin in the assessment of obesity and insulin in the assessment of insulin resistance in patients with abnormal body mass index." (PMID 37373485, 2023). "It is known that obesity promotes changes in the activity of human colostrum cells via mechanisms involving hormones such as leptin, adiponectin, and melatonin; these hormones also promote the decreased release of intracellular calcium and decrease the apoptosis index in obese women." (PMID 36768983, 2023). "Despite no firm evidence, it is speculated that infants of mothers with obesity (and higher HM leptin concentrations) are likely to consume more leptin, which may negatively impact their growth." (PMID 37242254, 2023). "In the case of obesity caused by improper diet, high levels of leptin no longer fulfill their role and do not inhibit weight gain." (PMID 36834291, 2023). "Given this evidence, leptin may contribute to suboptimal and abnormal immune responses to infections in disorders at higher circulating leptin levels, among which obesity." (PMID 37217748, 2023). "Perhaps, this can be explained by the neuroprotective effect of leptin, which rises with obesity." (PMID 36845661, 2023). "Thus, in this review, we will highlight in vitro, in vivo, and clinical studies concerning the role of leptin in obesity-related cancers." (PMID 37509120, 2023). "Of note, acute leptin reduction after hyperleptinemia in the context of obesity exhibited a beneficial effect on obesity and insulin sensitivity, indicating that manipulation of circulating leptin level may provide a therapeutic strategy." (PMID 37547309, 2023). "Although studies on melatonin have transformed obesity research, therapeutic applications of this molecule are still limited due to the complexity and poor understanding of the relationship between melatonin and leptin." (PMID 38001815, 2023). "The leptin/leptin receptors axis may be a potential therapeutic target for obesity in patients with CP." (PMID 37509115, 2023). "Inhalation of patchouli essential oil or oral administration of Arq Zeera oil and its main component thymol reduced food intake and lowered elevated serum leptin levels in rats with obesity, implying that these materials reduced leptin resistance to modulate food intake." (PMID 37175666, 2023). "However, the interaction between leptin/obR signaling and M1 macrophages in the obesity-related neutrophilic airway inflammation mouse model needs to be further explored." (PMID 37488474, 2023). "Interestingly, levels of leptin, a major obesity-related adipokine, have been documented to positively correlate with non-small cell lung cancer (NSCLC)." (PMID 37509120, 2023). "Logically, obesity might be expected to be correlated with low leptin levels; however, this is only the case for 10% of obese individuals." (PMID 37064917, 2023). "Moreover, studies comparing children with normal weight and with obesity concluded that leptin levels are inversely related to tibial trabecular thickness." (PMID 36831188, 2023). "Obesity may also result from decreased leptin-mediated energy expenditure, and increased food consumption may be a counterregulatory mechanism secondary to heat loss." (PMID 37445827, 2023). "Therefore, since the human placenta is responsible for the production of adipokines, leptin has been implicated in various related pathologies of pregnancy such as GDM, obesity, fetal growth abnormalities, and metabolic dysfunction." (PMID 37497352, 2023). "Our hypothesis is that both ICV leptin injection and diet-induced obesity will lead to increased levels of norepinephrine in multiple organs, including the ovaries and the liver." (PMID 38069231, 2023).
Obesity (continued). "Furthermore, it should be noted that especially in individuals with overweight and obesity, the ability of leptin to inhibit appetite can be blunted." (PMID 36476162, 2023). "Obesity and MS are characterized by increased leptin and decreased adiponectin concentration." (PMID 37960185, 2023). "Moreover, through a detailed study of attributes of the biochemistry-balanced ML model, we were able to demonstrate that those with the highest IR predictive abilities (e.g., leptin/adiponectin ratio) were strongly related to the presence of obesity." (PMID 36833178, 2023). "Particularly, the groups HC2.5Hi, which provided 2.5 mg/kg Ce6 with a high irradiation dose, and HC5Hi, (Ce6 (5 mg/kg) with a high irradiation dose, showed the best anti-obesity activity through improved leptin, adiponectin, and serum lipid levels in high-fat diet-induced obesity in mice." (PMID 37513964, 2023). "Therefore, elevated sOBR/serum leptin (SL) ratio is an indicator of leptin resistance, which can be seen in obesity." (PMID 37128293, 2023). "Obesity is related to an increase in the secretion of leptin-a key adipokine for maintaining the body’s energy homeostasis (stimulating satiety and tissue sensitivity to insulin), which also, among others, regulates the tone of the vascular walls and reproductive functions." (PMID 36979669, 2023). "Moreover, 12 weeks of HIIT (running, 100% maximum aerobic speed, 3 sessions/week) decreased the blood leptin concentration and body fat mass, resulting from increased VO2max at post-intervention in young women with obesity." (PMID 37608837, 2023). "Another mechanism that may be involved in the increased RMR due to Se supplementation in people with overweight or obesity involves the effects of Se on insulin resistance and leptin." (PMID 37513551, 2023). "Therefore, it can be concluded that both adiponectin and leptin have a safeguarding role against obesity and cognitive frailty." (PMID 37363537, 2023). "Indeed, obesity, via increased leptin levels, exaggerated the neuroinflammatory response to LPS administration." (PMID 36769012, 2023). "However, recent studies suggest that leptin action is actually increased in obesity, and thus argue against the role of leptin resistance as a causal role in obesity." (PMID 37069175, 2023). "In conclusion, we suggest that Zn treatment may be effective in ameliorating obesity-related metabolic dysfunction, central leptin resistance and cognitive deficits." (PMID 36977735, 2023). "At hormonal levels, a stepwise increase in insulin and leptin and a reduction in ghrelin, with possible consequences on the imbalance of the gustatory signaling and food reward, has been found in subjects affected by OW and stages I–II obesity." (PMID 38313840, 2023). "Of note, leptin resistance is persistent in diet-induced obesity, raising the possibility that epigenetic reprogramming may be a causal factor for leptin resistance." (PMID 36512408, 2023). "However, little is known about how leptin/obR signaling participates in the pathogenesis of obesity-related neutrophilic airway inflammation." (PMID 37488474, 2023). "In obesity, high leptin levels fail to reduce appetite and increase energy expenditure." (PMID 37374075, 2023). "Furthermore, the obesity-related increase in serum leptin levels lowers the cortical bone density in the alveolar bone area, exacerbating alveolar bone loss." (PMID 38111655, 2023). "In addition, mRNA expression of genes, such as peroxisome proliferator-activated receptor-γ (PPARγ), CCAAT/enhancer-binding protein-α (C/EBPα), and leptin, is known increase in obesity." (PMID 37432154, 2023). "Periodontitis can also affect obesity by influencing leptin." (PMID 38111655, 2023). "Serum leptin levels were significantly increased in LepR-Cre Slc7a5fl/fl mice prior to the onset of obesity (7 weeks of age) and after the diagnosis of obesity (24 weeks of age)." (PMID 36862514, 2023).